KRAS (KRas proto-oncogene, GTPase)
Diseases named in the same sentence as KRAS in open-access papers (continued):
Sharing a sentence is not in itself a finding about the gene and the disease.
tumor (continued). "Interestingly, we found a significant decrease in STAT3 expression levels in KRAS mutant human tumours compared with lung tumours with wild-type KRAS in the first cohort of smoking patients." (PMID 25734337, 2015). "Second, we did not examine other less common mutations in KRAS codons 61, 117 and 146, which also contributed to the oncogenic transformation of tumor cells." (PMID 26042813, 2015). "Patients with KRAS mutated MSS tumours appear more likely to have disseminated disease, but recurrences in stages II and III disease were not more frequent when MSS tumours were KRAS mutated." (PMID 25884297, 2015). "Thus, wild-type KRAS promotes xenograft tumor growth of oncogenic HRASG12V-transformed cells expressing constitutively active PI3K in a manner dependent upon C118." (PMID 25902334, 2015). "Interestingly, of the 8 PDXs that demonstrated tumor regression, 6 (75%) were KRAS/BRAF mutant and PIK3CA wild-type, whereas the other 2 were either all wild-type, or all mutant for RAS/RAF or PI3KCA." (PMID 26439693, 2015). "A number of studies have revealed the ‘RAF inhibitor paradox' in which CRAF is activated and tumour growth enhanced for tumours with activating mutations in KRAS but not BRAF." (PMID 26333361, 2015). "In the absence of PTF1A, a persistent inflamed microenvironment may have tumor promoter-like activity, enhancing KRAS-MEK-ERK signaling to induce transformation." (PMID 26151762, 2015). "Furthermore, in contrast to dMMR CRC, data on the presence of KRAS oncogenic mutations in proficient MMR (pMMR) CRC and their relationship with tumor progression are scarce." (PMID 26042813, 2015). "Consequently, KRAS oncogenic activation was shown to be an important mediator of tumor cell invasion and metastasis in pMMR tumors." (PMID 26042813, 2015). "While PTEN loss or KRAS(G12V) alone do not produce any detectable tumors, the combination of both mutations appear to synergize to promote robust primary tumor growth." (PMID 26497685, 2015). "In addition, testing of cfDNA demonstrated acceptable concordance (BRAF, 91%; EGFR, 99%; KRAS, 83%; PIK3CA, 91%) with standard of care mutation analysis of primary or metastatic tumor tissue obtained during clinical care." (PMID 25980577, 2015). "Neither PTEN loss nor KRAS activation resulted in primary tumor development, suggesting that cells with either alteration do not confer rapid growth rates and are likely unable to overcome the challenge of growth arrest." (PMID 26497685, 2015). "With the exception of KRAS, these genes are usually regarded as tumor suppressors." (PMID 25794154, 2015). "The KRAS genotype of the tumor samples was analyzed using the Luminex® assay." (PMID 26490659, 2015). "KRAS and BRAF mutations are currently assessed in the primary tumor tissue." (PMID 25628770, 2015). "The remaining 2 patients tested WT for KRAS in the primary tumor." (PMID 26498594, 2015). "Five studies compared tumour response rate in subgroups stratified by KRAS status." (PMID 26557880, 2015). "When compared in FFPE tumor samples with or without mutations, miR-31-5p/3p expression levels were found not to be associated with KRAS/NRAS mutational status (P = 0.901 and P = 0.813, respectively)." (PMID 26497852, 2015).
tumor (continued). "Structural and functional analyses have indicated that MEK inhibitors with superior anti-tumor activity in KRAS-driven tumors form a strong hydrogen-bond interaction with the backbone amide of S212 in MEK that is critical for blocking MEK feedback phosphorylation by wild-type RAF." (PMID 26439693, 2015). "Additionally, this analysis confirms previous co-operative mutations (e.g., KRAS and LKB1) and reveals potentially new, testable gene pairs that are selected for during tumor formation." (PMID 26047463, 2015). "This has important implications for diagnostic testing, because we would not have detected mutations in KRAS or RPTOR in the upper regions of the tumor mass." (PMID 25729435, 2015). "Four patients (1.3%) did not have tumor KRAS mutation status tested prior to starting panitumumab treatment." (PMID 26491871, 2015). "Subject to the knowledge of the KRAS status of the tumor, the targeted agent with which to combine first-line chemotherapy should still be selected based on patient and physician assessment of the risk:benefit ratio of cetuximab compared with that of bevacizumab in individual patients." (PMID 26468218, 2015). "In summary, KRAS codon 12 mutation, but not codon 13 mutation, is associated with lymph node metastasis and higher tumor stages." (PMID 25929517, 2015). "It is interesting to note that though KRAS was frequently mutated in primary tumours, no mutations were called for this gene in the 35 sequenced metastases, including those 5 samples with paired, KRAS-mutated primary tumours." (PMID 26647728, 2015). "In the present study we analyzed the prognostic and predictive value of BRAF/KRAS mutations and tumor tissue availability in patients with non-resectable mCRC included in a prospective population-based study." (PMID 26121270, 2015). "This re-review by a pathologist identified very low tumor percentage in two of the four KRAS wild-type samples that we sequenced, which emphasizes the invaluable caveat of appropriate sample quality control assessment by a trained pathologist prior to nucleic acid preparation and sequencing." (PMID 25594743, 2015). "In 2015, le Rolle and colleagues found that CXCL1 overexpression is a poor prognostic marker on metastatic CRC, furthermore, CXCL1 inhibition could suppress tumor cell growth of KRAS mutant CRC cells." (PMID 26208990, 2015). "By using an antibody directed at KRAS (but at a nonmutated protein), we expected to visualize mutated KRAS protein in tumor cells of mutated carcinomas (or at least to detect an “overexpression” in mutated cases)." (PMID 25983749, 2015). "In present analysis, GEMOX plus erlotinib group included only 5 patients with KRAS mutant tumor." (PMID 26189560, 2015). "Of the 90 tumor samples, 46 were KRAS MT while the remaining 44 were KRAS WT." (PMID 26468985, 2015). "In 6p+12p, loss of the p21-encoding CDKN1A and the p38-encoding MAPK14 on 6p, and gain of KRAS on 12p, combined but not separately, can lead to transformation of human normal to tumor cells." (PMID 25875127, 2015). "Based upon this theory a treatment break after developing acquired anti-EGFR resistance may allow the dominant clone that is KRAS-wt to repopulate and render a tumor sensitive to anti-EGFR therapy." (PMID 26474549, 2015). "The reason for these results may be that most of the tumor cells were wild-type KRAS subclones that could respond to anti-EGFR antibody treatment in the early stages of treatment." (PMID 26701781, 2015).
tumor (continued). "ERBB2 mutations may be of particular interest because the two tumors that include KRAS mutations also include ERBB2 mutations, and KRAS and ERBB2 are thought to function jointly to drive tumor growth." (PMID 25594743, 2015). "We isolated single PDX cells from a KRAS-driven tumor, which represents 25–33 % of LUADs." (PMID 26084335, 2015). "High sensitivity in relation to KRAS mutation assays is crucial in minimizing the risk of false negative results in tumor specimens containing low quantities of mutated DNA." (PMID 26701781, 2015). "Furthermore, regorafenib showed OS and PFS benefit in both KRAS-wild-type and KRAS-mutant tumor subgroups." (PMID 25213161, 2015). "Likewise, co-treatment with let-7b mimic reduced the IC50 of gemcitabine to a much greater extent in KRAS mutant tumor cells than in KRAS wild-type cells." (PMID 25946136, 2015). "Importantly, because there are a certain number of mCRC patients with molecular alteration other than KRAS exon 2, further refinement of tumor-specific genetic markers is needed to improve the efficacy of anti-EGFR therapy." (PMID 25886136, 2015). "Three (1.0%) of the 302 patients tested for KRAS tumor status prior to their first dose of panitumumab had mutant (n = 2) or unknown (n = 1) KRAS status (none were receiving concurrent oxaliplatin-containing therapy." (PMID 26491871, 2015). "In comparison, by 2012 in our medical records review, 1% (3/302) of patients tested for KRAS tumor status prior to their first dose of panitumumab had mutant or unknown KRAS status (none were receiving concurrent oxaliplatin-containing therapy)." (PMID 26491871, 2015). "Patients with G13 KRAS mutant tumor showed a median PFS of 3.9 months." (PMID 26416458, 2015). "However, recent studies identified that tumours with a KRAS wild type (KRAS WT) and positive EGFR expression as measured by IHC was not predictive of anti-EGFR efficacy." (PMID 26149458, 2015). "Our observations that decrease CXCL1 secretion by SW620 cells inhibited their anchorage-independent and xenograft tumor growth are supported by similar findings in KRAS mutant LS174T CRC cells, whose malignant growth were inhibited by CXCL1 siRNA or neutralizing α-CXCL1 antibody." (PMID 26104296, 2015). "KRAS p.G12V and BRAF p.V600E mutations occurred together in a further tumor sample." (PMID 25568935, 2015). "The concept that not all KRAS mutations behave in the same way and that they differently impact on tumor progression has been addressed." (PMID 26416458, 2015). "In particular, KRAS genotyping of primary tumor tissues or metastatic lesions is strongly recommended by the National Comprehensive Cancer Network (NCCN) Clinical Practice Guidelines in Oncology version 3 (2008) in patients with mCRC prior to any therapy that includes anti-EGFR mAbs." (PMID 24884535, 2014). "In PDTX models, following a 30-day exposure to PF-502, PD-901 or the combination, the combination demonstrated enhanced reduction in tumor growth as compared to either single agent regardless of KRAS or PI3K mutational status." (PMID 25401499, 2014). "In the overall analysis, significant associations were found between most anthropometric factors and risk of KRAS-mutated and BRAF wild type tumours, whereas only BMI was associated with KRAS wild type tumours, and none of the anthropometric factors were associated with risk of BRAF-mutated CRC." (PMID 24918610, 2014). "When the total number of patients with a KRAS mutation was analyzed regardless of tumor type, the rate of clinical benefit of patients treated with a MEK inhibitor--containing therapy was higher than that of those treated with other therapies (p=0.02)." (PMID 25313136, 2014).
tumor (continued). "This resistance was specifically linked to changes in the level of phosphorylation of 4E-BP1, and was not evident in either a tumor with wild type KRAS or a tumor with a PIK3CA mutation in addition to KRAS." (PMID 24393708, 2014). "The effect of miR-30b in tumor growth was mediated through targeting many genes including KRAS." (PMID 25433809, 2014). "KRAS PTEN tumours are uniquely responsive to mTOR inhibition." (PMID 24717934, 2014). "However, we did not see any significant associations of EDMs with clinicopathological parameters, including sex, age, tumor location and tumor stage, CIMP, KRAS, and BRAF mutations." (PMID 25124163, 2014). "On the other hand, even with KRAS mutational testing, there are still many patients with KRAS wild-type tumours that do not respond to treatment with cetuximab or panitumumab." (PMID 25361007, 2014). "Amplification of the oncogene KRAS and loss of tumour suppressor SMAD4 may fuel cancer progression in this tumour." (PMID 25351503, 2014). "Understanding the molecular mechanism of miRNA-mediated regulation of KRAS by characterizing tumor suppressive miRNAs and oncoproteins that regulate tumor suppressive miRNAs in the KRAS signaling pathway would be beneficial for developing treatments in the clinic." (PMID 25433809, 2014). "The results from the present study appear to be somewhat different in that a high BMI was found to be associated with risk of KRAS-mutated tumours in men but not in women, with a significant interaction of sex with BMI regarding this risk." (PMID 24918610, 2014). "Because RAS can promote tumor angiogenesis through the induction of the IL-8 cytokine, and because IL-8 is upregulated by KRAS in an IKKβ-dependent manner, we hypothesized that CmpdA would inhibit tumor angiogenesis." (PMID 24955217, 2014). "In summary, BRAF mutations appear to occur more frequently in CRC tumours with MSI-high characterised by dMMR, posing as strong OS prognostic factor, but also presence of KRAS mutations in patients proficient in MMR may suggest highest recurrence rate." (PMID 25361007, 2014). "Similarly, a more recent study found that mutant KRAS shRNA-knockdown in NSCLC suppresses tumor growth also sensitizing tumor cells to p38 and EGFR inhibitors." (PMID 25593996, 2014). "In this study, we show that the combination of a selective MEK inhibitor and a PI3K/mTOR inhibitor is effective against tumor cell lines refractory to gefitinib by three different mechanisms: an EGFR gatekeeper T790M mutation, MET amplification, and KRAS/PIK3CA mutation." (PMID 24939055, 2014). "When patients were divided according to their combined plasma/tissue KRAS status, the best prognosis was observed in patients without mutations in either tumor or plasma, while the worst was evident in patients with mutations in both tissues." (PMID 25491325, 2014). "Interestingly, in two polygenomic breast cancers, subpopulations with increasing genomic complexity followed a linear pattern geographically in the tumor and in one of the two tumors, a subclonal KRAS amplification was identified." (PMID 25928070, 2014). "Only a small percentage of patients showed KRAS mutations in plasma but not in tumor tissue (5% by either method)." (PMID 25491325, 2014). "In NKX2-1 negative mice models with KRAS mutations, reduced tumor volume was seen when TTF-1 expression was induced." (PMID 25594059, 2014). "Interestingly, a synthetic lethal screen to identify genes that, when inhibited, cooperate with MEK inhibitors to effectively treat KRAS mutant tumours identified BCL-XL as the most prominent target." (PMID 26556430, 2014). "BRAF mutations seem to occur more frequently in CRC tumours with MSI-high characterised by dMMR, and poses as strong OS prognostic factor, however presence of KRAS mutations may suggest highest recurrence rate." (PMID 25361007, 2014).
tumor (continued). "KRAS alterations could be identified noninvasively 5–10 months before radiographic disease progression by analyzing cell-free circulating tumor DNA (ctDNA)." (PMID 24811491, 2014). "Of note, the patient with the highest TTF while on an mTOR-based regimen had a tumor that did not harbor KRAS mutations." (PMID 24586741, 2014). "Notch1 is required for tumor initiation in the KRAS-driven lung ADC mouse model." (PMID 25004243, 2014). "Another use is for genetic analysis including gene expression analysis of tumor biomarkers such as HER2/E-cadherin by qRT-PCR, and mutation analysis of oncogenes/suppressor oncogenes such as EGFR/KRAS by PCR-based whole genome amplification (WGA) and subsequent direct sequencing." (PMID 24523941, 2014). "Considering the final endpoint, using 454-NGS we detected a KRAS mutation in the 75.7% of adenocarcinomatous and pre-neoplastic lesions (in the 70% of PDAC cases, in the 83.3% of IPMNs and in the 66.7% of inoperable neoplasias)." (PMID 24504548, 2014). "Overall, either type of tumor tissue, primary or secondary CRC (with a putative exception for metastatic lymph nodes), could be useful as a source to detect KRAS mutations in selecting patients to be addressed to anti-EGFR therapy." (PMID 25202344, 2014). "Overall, KRAS mutations were more frequent in tumor than in plasma samples, and this was independent of the assay; KRAS mutation rates in tissue versus plasma were 38% vs. 17% with direct sequencing (p < 0.001) and 47% vs. 31.4% with PNA-PCR (p < 0.001)." (PMID 25491325, 2014). "Several studies suggest tumor cells harboring mutant-KRas may be primed to undergo epithelial mesenchymal trans-differentiation, for example." (PMID 25538889, 2014). "Methylation data was analysed using a recursively partitioned mixture model and investigated for associations with clinicopathological and molecular features including age, Helicobacter pylori status, tumor site, patient survival, microsatellite instability and BRAF and KRAS mutations." (PMID 24674026, 2014). "In relation to codon 13, some studies have shown that mutations in this codon could be less aggressive than in codon 12 and that patients with KRAS Gly13Asp mutant tumours could benefit from anti-EGFR therapies." (PMID 24720724, 2014). "Each patient was classified as KRAS positive (i.e. KRAS mutations in tumor and plasma samples), KRAS negative (i.e. KRAS wild-type in tumor and plasma samples), or with discordant KRAS status in tumor and plasma samples." (PMID 25491325, 2014). "Up-regulation of miR-217 could decrease the expression of KRAS protein, thereby inhibiting tumour cell growth." (PMID 25199527, 2014). "We found that tumours in KRAS PTEN mice exhibit a remarkable dependence on mTOR signalling." (PMID 24717934, 2014). "Although KRAS status did not correlate with pathological T factors, mean tumor diameter was larger in patients with KRAS mutations (3.46 ± 1.99 cm) than in those with wild-type KRAS (2.99 ± 1.36 cm; P = 0.001)." (PMID 25152277, 2014). "Overall, although we found that KRAS mutated tumors display a distinct methylation profiles, there was association with neither tumor multiplicity nor CIMP status." (PMID 24643221, 2014). "They further found that repression of miRNA-143/145 cluster could trigger a tumor-promoting feedforward pathway by targeting KRAS and Ras-responsive element-binding protein (RREB1)." (PMID 24587996, 2014). "Recent data also indicate that the prognostic value of the tumor growth pattern in stage I–III CRC is independent of central molecular features including KRAS, BRAF, and PIK3CA mutations as well as MSI-status and CIMP methylation." (PMID 24600585, 2014). "Given the implicated role of ACK-1 in EGFR, KRAS and ALK signaling, we suggest a potential therapeutic niche for combination studies with bosutinib selecting for patients with ACK-1 overexpression, specifically in circumventing tumor metastasis and recurrence." (PMID 24461128, 2014).